IL6 (interleukin 6)
Diseases named in the same sentence as IL6 in open-access papers (continued):
Sharing a sentence is not in itself a finding about the gene and the disease.
colitis (continued). "Multiple interleukins secreted by lymphocytes mediate their pro/anti-inflammatory effects, and inhibition of proinflammatory cytokines (IL-6, IL-1β, IL-12, and IL-23) is an effective strategy to ameliorate colitis." (PMID 36145301, 2022). "Other TCMs, such as Wuweiwan (WMW Meiwan, WMW), reduce CAC (colitis and colorectal cancer) by regulating the balance between “tumour promoting bacteria” and “carcinoma suppressing bacteria” and the NF-kB/IL-6/STAT3 pathways." (PMID 35431939, 2022). "Accordingly, the increased concentrations of pro-inflammatory cytokines in the colitis mice, such as IL-6, IFN-γ, and TNF-α, were all significantly decreased by SFN treatment." (PMID 35832050, 2022). "We also observed that DSS‐induced colitis in Il34−/− rats led to increased levels of pro‐inflammatory cytokines Il6, Il1b, Il22 and a trend for an increase for Il17a, all involved in gut inflammation, whereas Ifng was decreased." (PMID 36030499, 2022). "In TNBS-induced colitis in rats, the colonic mRNA expression and protein level of IL-6 peak at day 7 and then start to gradually decline to normal levels." (PMID 35766160, 2022). "Here, we report that the PI3K/PTEN signaling pathway in dendritic cells enhances IL-6 production in a model of DSS-induced colitis." (PMID 35514976, 2022). "Our study showed that blockage of BAFF activity effectively inhibited IL-1β, TNF-α, and IL-6 gene expression in colonic tissues from DSS-induced colitis mice." (PMID 35320937, 2022). "Correspondingly, the expression levels of TNF-α and IL-6, which were secreted by macrophages, were significantly decreased in the plasma of colon cancer and colitis mice after injection of HUC-MSCs." (PMID 35694239, 2022). "TNF-α, IL-6, IL-1β, and IL-2 are involved in many inflammatory visceral pain diseases like visceral pain after colitis, surgery, and endometriosis." (PMID 35642022, 2022). "Similar to ALG, B. animalis and HDCA exerted a strong anti-inflammatory effect in DSS-induced colitis by downregulating inflammatory cytokines (interleukin-1β [IL-1β], IL-6, and tumor necrosis factor alpha [TNF-α])." (PMID 36219101, 2022). "On the other hand, serum IL6 was significantly reduced in the colitis mice receiving FMT from colitis mice treated with HA relevant to the control group." (PMID 36558542, 2022). "Taken together, we identified the PI3K/PTEN signaling pathway in dendritic cells as a driver of IL-6 mediated Th1 responses which is triggered upon microbiota dependent inflammation in a model of DSS-induced colitis." (PMID 35514976, 2022). "Collectively, our data suggested that the Rasgrp1 3’ UTR aggravates the development of colitis by promoting IL-6 protein production." (PMID 36385095, 2022). "We then evaluated the effect of WT161 on IL-1β and IL-6 in the supernatant culture of colonic explants isolated from DSS-induced colitis mice and activated peritoneal macrophages induced by LPS + DSS." (PMID 35330829, 2022). "Dysfunction of the colonic epithelial barrier can also promote the occurrence and development of colonic inflammation, with pro-inflammatory cytokines such as IL-1β, IL-6 and TNF-α playing a key role in the development of inflammation." (PMID 35514335, 2022). "CD4 TH-17 cells secreting IL-17, IL-6, and IL-8 appear in patients who develop grade >3 colitis (with anti CTLA-4)." (PMID 35774996, 2022). "Oral administration of NK151, NK175, or their (4:1) mix suppressed cGm-induced colitis in mice: they suppressed colonic myeloperoxidase activity, IL-1β and IL-6 expression, and the NF-κB+CD11c+ cell population, while significantly increasing IL-10 expression." (PMID 35631220, 2022). "Macrophages in the colon will trigger and exacerbate DSS-induced colitis by releasing cytokines, such as IL-6, TNF-α, and IL-1β." (PMID 36189321, 2022).
colitis (continued). "This beneficial effect was reported to be mediated through the inhibition of TLR4-NF-κB-NLRP3 axis and, consistently, the pro-inflammatory cytokines (tumoral necrosis factor-α (TNF-α), IL-1β, IL-6, IL-2) levels were also suppressed in the treated colitis mice." (PMID 36558455, 2022). "In our study, IL-6 levels were higher in patients with thyroiditis and colitis, while IL-22 and SCF levels were higher in patients with colitis." (PMID 36159840, 2022). "The results showed that, compared with the control group, the levels and expression of pro-inflammatory factors TNF-α, IL-1β, and IL-6 in colon tissues from colitis mice were significantly increased." (PMID 35387334, 2022). "A prior study suggested that the elevation of colonic TNF-α, IL-6, and IL-1β levels in colitis mice were induced by DSS, which is consistent with our findings." (PMID 35681301, 2022). "This leads to the activation of NF-κB signaling and the expression of pro-inflammatory cytokines such as TNFα and IL-6, in the in vivo mouse model of colitis." (PMID 34983535, 2022). "Western blot analysis of TNFα and IL6 in colon samples confirmed an increase in these two proteins in colitis mice, which was suppressed by BBR." (PMID 36528592, 2022). "The effects of roflumilast on serum levels of TNF-α, IL-2, and IL-6 in rats with trinitrobenzenesulfonic acid (TNBS)-induced colitis (n=8)." (PMID 35239781, 2022). "Although the administration of PD does not alter most cytokine levels, we did observe a significant increase in IL-6 production in 300 mg/kg PD treatments in DSS- induced colitis mouse model." (PMID 35933374, 2022). "Many polysaccharides from TCMs have been demonstrated to inhibit the IL-6/STAT3 pathway in DSS-induced colitis mice." (PMID 36341374, 2022). "To further assess the effect of LBGH on DSS-induced colitis in mice, we measured the levels of pro-inflammatory cytokines including IL-1β, IL-6, and TNF-α in serum as well as in colonic tissue through ELISA kits." (PMID 36033869, 2022). "Targeting oncomiRs such as miR-21 and miR-181-b, and lack of PDCD4 in colitis and CAC mice models have been associated with enhanced IL-6 production, intensified activity of STAT3 signaling pathway, enhanced colitis and proliferation of tumor cells." (PMID 35410210, 2022). "We found that Magnolia officinalis bark extract (MBE) prevented weight loss and suppressed the activation of the proinflammatory cytokine IL6 in DSS-induced colitis." (PMID 36552643, 2022). "Recent studies suggest that high levels of pro-inflammatory cytokines, including IFNγ, TNFα, IL1β, IL6, and MCP1, are implicated in DSS-induced colitis." (PMID 35888062, 2022). "Increased LGALS9 expression in humans is positively correlated with augmentation of T-cell markers and proinflammatory cytokines such as IL1B and IL6 in the affected intestines, which also has positive correlation to the severity of colitis." (PMID 35794311, 2022). "We also found that mEVs decreased the expression of pro-inflammatory factors (IL-1β, IL-6 and IL-17A) in colitis." (PMID 35893911, 2022). "Scutellaria baicalensis polysaccharides also improved colitis by regulating Firmicutes and Roseburia abundance, enhancing the concentration of butyric acid, and reducing the levels of IL-6, IL-1β, and TNF-α." (PMID 35454671, 2022). "NF-κB mediated the production of various proinflammatory cytokines, such as IL-6, TNFα, and IL-1β, which regulated inflammatory responses in colitis induced by DSS (M. L. Chen and Sundrud 2016; Neurath 2014; Fantini and Pallone 2008)." (PMID 35433693, 2022). "SIRT6 transgenic mice showed lower levels of pro-inflammatory cytokines like TNF-a, IL-1β, and IL-6 in the dextran sulfate sodium salt (DSS)-induced colitis model than normal mice." (PMID 35517808, 2022). "The relative abundance of Streptococcus in feces has a positive correlation with serum IL-6 level in mice models of colitis and with colonic mucosal TLR2 receptor expression in ulcerative colitis patients, respectively." (PMID 36389768, 2022).
colitis (continued). "Il-1β and Il-6, proinflammatory cytokines upregulated in the hippocampus of our mice with acute colitis, are potent suppressors of neurogenesis." (PMID 36232813, 2022). "The secondary BAs consistently showed a significant reduction in the mRNA levels of pro-inflammatory cytokines (Il6, Il1β, Tnfα) and some monocytes-related chemokines (Ccl2, Ccl7, Ccl8) in colitis mice." (PMID 36050867, 2022). "In another study conducted on dextran-sodium-sulfate (DSS)-induced colitis in rats, the effects of neem leaf extracts on the levels of IL-6 and TNF-α were evaluated." (PMID 36145202, 2022). "IL-6 is elevated in the inflamed intestinal mucosa, and suppression of IL-6 signaling relieved colitis in mouse models and also had beneficial effects in a clinical trial of patients with Crohn’s disease." (PMID 35976342, 2022). "IL-1β and IL-6 are two important pro-inflammatory factors positively correlated with colonic inflammation." (PMID 35684007, 2022). "GrTP showed a similar efficacy to sulfasalazine in reducing inflammatory markers (TNFα, IL-6 and serum amyloid A), restoring concentrations of antioxidant agents (glutathione and cysteine) and attenuating colitis in murine models of both UC and CD." (PMID 35407131, 2022). "For example, fermented millet bran can significantly reduce serum pro-inflammatory cytokines TNF-α and IL-6, thus improving recurrent colitis, and has a significant protective effect on colonic inflammation." (PMID 35885325, 2022). "B. bifidum BGN4-SK significantly ameliorated the symptoms of DSS-induced colitis, increased the expression of tight junction genes (claudin and ZO-1), and decreased pro-inflammatory cytokines IL-6, IL-1β and TNF-α." (PMID 35672695, 2022). "Mice with DSS-induced colitis exhibited more anxiety and less social behaviour than control mice and occurred in parallel with increased circulating IL-6, NPY, and IL-18 levels as well as an increase in hypothalamic Cox-2 mRNA." (PMID 34983592, 2022). "In the acute DSS-induced mice colitis model, EA attenuated colitis severity slightly through the reduction of inflammatory mediators (IL-6, TNF-α, and IFN-γ)." (PMID 35805952, 2022). "Vitamin C insufficiency resulted in decreased IL-22 and mucin production and increased the production of IL-6 in the DSS-induced colons of vitamin C-insufficient KO mice, which seems to cause severe colitis." (PMID 36142515, 2022). "In IBD patients and some animal models with colitis, there are high levels of IL-6 expression and high levels of STAT3 phosphorylation, which are related to disease activity." (PMID 35982893, 2022). "DSS-induced colitis in rodents increases plasma levels of corticosteroids and pro-inflammatory cytokines, such as elevation of interleukin-6 and GRO-alpha in the brain." (PMID 35976343, 2022). "In the present study, we observed that plasma TNF-α, IL-6, and IL-17 were significantly increased in mice with colitis." (PMID 36009796, 2022). "The oral administration of thinned apple polyphenols attenuated gene expression of IFN-γ, TNF-α, IL-1β, IL-6, IL-17, and IL-22 in the colons of mice with colitis." (PMID 35741912, 2022). "In accordance with our study, Th1-derived TNF-α, Th17-derived IL-1β, and IL-6 were significantly increased in DSS-induced colitis mice compared to the control." (PMID 36176442, 2022). "In vitro, EsA treatment increased the number of DSS-inhibited bowel movements and body weight, improved the histological score of colitis, and inhibited the inflammatory response by reducing IL-6 and TNF-α levels in rats." (PMID 36091585, 2022). "In a dinitrobenzene sulfonic acid-induced colitis model, guanosine lowered IL-1β, IL-6, and TNF-α mRNA levels and downregulated the expression of NF-κB p65 and the levels of ROS and nitrite." (PMID 36235070, 2022). "In the present study, the DSS-induced colitis was ameliorated by the H2S donor NaHS, which was manifested by improved clinical parameters and decreased serum levels of IL-6 and TNF-α." (PMID 36189321, 2022).
colitis (continued). "The study revealed a high potency of (HT) in suppressing inflammation and alleviating colitis symptoms via downregulation of IL-6, IL-1β, TNF-α, and myeloperoxidase enzyme." (PMID 35990343, 2022). "ST2-dependent IL-33 signalling disrupts intestinal barrier integrity resulting in increased serum LPS and IL-6 induction consistent with enhanced colitis." (PMID 36263033, 2022). "Regarding the molecular mechanism, PE-EPS reduced the enhanced expression of inducible nitric oxide synthase (iNOS), cyclooxygenase-2 (COX-2), and pro-inflammatory cytokines (TNF-α, IL-6, and IL-1) in the colon tissue of colitis-induced mice." (PMID 36080669, 2022). "ERAP1 is also known to cause shedding of IL-6, further linking ERAP1 and regulation of IL-6 in colitis." (PMID 35246034, 2022). "Our in vivo studies showed that apigenin inhibited TNF-α, IL-6, and IL-1β secretions in colitis of DSS-induced mice." (PMID 36590200, 2022). "L-fucose is found to decrease elevated levels of TNF-α, IL-1β, and IL-6 in serum and colonic tissues of mice with a model of colitis." (PMID 36421993, 2022). "For studying the therapeutic action of BBR on colitis in vitro, IL-6 (10 ng/ml) was applied for stimulating Caco-2 cells and NCM460 cells to obtain an in vitro model, and incubation of the cells was with BBR (50 mM)." (PMID 35259053, 2022). "NK151, NK173, and NK175 alleviated iGm-induced colitis: they decreased IL-1β and IL-6 expression, while IL-10 and claudin-1 expression increased." (PMID 35631220, 2022). "Colitis rats supplemented with 12 mg CAP/kg bw for 4 weeks decrease serum IL-6 levels and protein expression of TRPV1 and TRPA1 in the colon, and increase serum SOD and CAT activities and colonic IL-10 levels." (PMID 35269566, 2022). "In particular, the expression of the pro-inflammatory cytokines TNF-α and IL-6 correlates positively with the severity of colitis." (PMID 36159466, 2022). "The lamina propria T cells increase the expression of IL-1, IL-6, and IL-8 during the process of colitis." (PMID 35327312, 2022). "El-Mahdy and his workmates reported that mesalazine can enhance anti-inflammatory effects to attenuate progression of oxazolone-induced colitis by restoring IL-10 and ZO-1 levels and limiting IL-6/STAT-3 trans-signaling." (PMID 35388299, 2022). "The main cellular mechanism of Res resistance to dextran sodium-sulphate-induced colitis is achieved by down-regulating the expression of inflammatory molecules such as IL-6, IL-1β, IFN-α and TNF-α." (PMID 34944291, 2021). "The in vivo results revealed that acute oral administration of GO increased the extent of colitis, accompanied by the release of pro-inflammatory cytokines (IL-6, IL-17, and IFN-γ) and apparent apoptosis in the intestinal mucosal epithelium." (PMID 33766052, 2021). "Berberine combined with carboxylmethyl chitosan by arylboronic ester can significantly improve the symptoms of colitis and colon damage by regulating IL-6 expression and remodeling the intestinal microbiota." (PMID 35046810, 2021). "Exposure to RS led to colon shortening, induced myeloperoxidase activity and NF-κB activation (p-p65 to p65 ratio), and increased TNF-α and IL-6 expression in the colon, leading to the outbreak of colitis." (PMID 34391441, 2021). "Compared with the mice in the sham group, an ELISA revealed that pro-inflammatory cytokine levels, including those of TNF-α, IL-1β, and IL-6, increased significantly in the murine model of colitis." (PMID 34594215, 2021). "IL‐6 was also identified to be positively correlated with severity of colitis in several mouse models." (PMID 33491282, 2021). "In this study, LD4-PDT treatment significantly inhibited TNF-α, IL-1 and IL-6 expression, and consequently reduced the severity of colitis in UC model." (PMID 34744725, 2021). "The levels of TNF-α, IL-1β, and IL-6 in colon tissues of colitis mice were elevated by contrast with those in the Model group." (PMID 34055024, 2021).
colitis (continued). "Intraperitoneal injection of LPS induced colitis: it induced colon shortening, IL-1β, IL-6, and TNF-α expression and suppressed IL-10 expression in the colon." (PMID 33985438, 2021). "A study on colon cancer has found that intestinal microbes can stimulate the expression of IL-6 and IL-1β, promote the expansion of Th17 cells, and thus increase the resistance to colitis and colon cancer." (PMID 34485534, 2021). "The total histology scores for colitis, as well as the colonic mRNA expressions of IL-1β, IL-6, and IL-10 were higher after the sympathectomy, compared to the sham." (PMID 34884737, 2021). "Results from ELISA confirmed that chrysophanol suppressed the production of serum TNFα and IL-6 in the colitis model." (PMID 33802855, 2021). "Among the cytokines, IL-6, which is one of the prominent proinflammatory cytokines in murine colitis models and IBD patients, was found to be significantly enhanced in Qa-1b−/− mice without additional inflammatory stimulus." (PMID 34911745, 2021). "On the contrary, IFN-γ, IL-17, TNF-α, and IL-6 are pro-inflammatory factors usually strongly exacerbating the inflammation cascade in colitis." (PMID 34090510, 2021). "Reducing TNF-α and IL-6 in mice with colitis was considered to be a logical target for the treatment of colitis." (PMID 34195297, 2021). "On the other hand, we observed significant reduction in TNFα expression in the gut on day 5 of DSS colitis and a similar trend for IL-6." (PMID 33986741, 2021). "The expression levels of TNF-α and IL-6 were also increased in PBLDIEC−/− mice compared with WT mice with TNBS-induced colitis." (PMID 34059646, 2021). "In animal models of colitis as well as in small-scale therapeutic trials in CD, blocking IL-6 with monoclonal antibodies has been demonstrated to be effective." (PMID 34746207, 2021). "UAMC-00050 treatment also significantly decreased protein levels of TNF-α, IL-1β, IL-6 and IL-17 present in the colons of the colitis animals." (PMID 34248633, 2021). "We showed that FAHF-2 suppresses TNF-α, IFN-γ, IL-1β, IL-6, IL-12 and IL-17 production from both PBMCs and inflamed colonic mucosa from pediatric subjects with CD, and abrogates murine colitis in the CD45RBhi transfer model." (PMID 34926527, 2021). "Consistently, DSS-induced colitis rats exhibited upregulation of IL-17A and IL-6 and downregulation of IL-10 and TGF-β1 in the colonic tissues." (PMID 33722292, 2021). "Netrin-1 also modulates colon-kidney cross talk through reducing both the production and activity of IL-6 as demonstrated in a mouse model of DSS-colitis." (PMID 35250531, 2021). "IL-1β and IL-6 have been elucidated as potent pro-inflammatory cytokines that stimulate several immune cells in colitis conditions." (PMID 33802855, 2021). "This study explored the potential role of miR‐223 in dextran sodium sulfate (DSS)‐induced colitis and its involvement in the IL‐6/STAT3 pathway during the pathogenesis of colitis." (PMID 33332758, 2021). "Cinacalcet significantly reduced both the expression and secretion of TNFα, IL-1β, and IL-6 in the colons of mice with DSS-induced colitis." (PMID 34880751, 2021). "It was shown that upon CIN-102 treatment, decreased mRNA levels of the pro-inflammatory cytokines IL-1β and TNF-α and increased expression of IL-6 was noted in colonic tissue in mice suffering from colitis." (PMID 34106933, 2021). "And IL-6 contributed to colitis-induced platelet responses including thrombocytosis and platelet hyperreactivity via the maturation and activation of megakaryocytosis." (PMID 33390844, 2021). "The latest experimental and clinical data show that pro-inflammatory cytokines such as TNF-α, IL-1β and IL-6 play an important role in the pathogenesis of colitis." (PMID 34551815, 2021). "Previous studies in a mouse model of colitis have demonstrated that mice with IEC-specific deletion of Stat3 display increased IL-6 expression." (PMID 33673239, 2021).